IL9 (interleukin 9)
Diseases named in the same sentence as IL9 in open-access papers (continued):
Sharing a sentence is not in itself a finding about the gene and the disease.
tumor (continued). "Importantly, the authors found that DTA-1 also prevent tumor development in an IL-9-dependent manner in non-transplantable models, including a chemical-induced colorectal cancer and the spontaneous K-Ras transgenic mouse model." (PMID 27832300, 2017). "In addition to IL-9, IL-21 secreted by TH9 cells also exerts critical anti-tumor effects." (PMID 27589682, 2016). "Furthermore, this IL-1β-induced TH9 differentiation increased IL-21, but not IL-9, secretion, and increased IL-21-dependent anti-tumor effects." (PMID 27589682, 2016). "Further studies will be required to determine whether transfer of T cells with increased IL-9 secretion capacity do not increase GVHD or whether such cells might improve graft-versus-tumor-effects." (PMID 23991087, 2013). "In vitro studies have shown that IL-9 could upregulate the P21CIP1 gene in tumor cells to directly induce the proliferation and inhibit the apoptosis of LY1 and LY8 cells in DLBCL, promote the survival of DLBCL cells, and reduce the sensitivity of tumor cells to chemical substances." (PMID 35211408, 2022). "Interestingly, the TAMs in the s.c.B16 tumor do not express IL-9R, which suggests the ability of IL-9 to regulate macrophages could be organ-specific or dependent on the local microenvironment." (PMID 35778404, 2022). "However, after PD-1 blockade with Nivolumab, these cells regained their proliferative and cytotoxic potential in vitro, measured by higher expression of granzyme B and perforin, while CD8+ T cells from tumor samples with low infiltration of IL-9+ cells did not respond to anti–PD-1 treatment." (PMID 33777008, 2021). "Meanwhile, they proved that HIF1α could directly regulate IL-9 expression by binding to the IL-9 promoter, and SIRT1-mTOR-HIF1α signaling-coupled glycolytic pathway positively regulated Th9 cell differentiation in vitro and in mouse tumor and allergic pulmonary inflammation models." (PMID 32377533, 2020). "Furthermore, eliminated CD4+T cells and/or CD8+T cells from wild-type tumor-bearing mice could not affect the tumor growth of mice, indicating that Th9 cells could directly promote the growth of tumor cells by secreting IL-9." (PMID 31414895, 2019). "In a B16-OVA tumor model, IL-7-treated OT-II Th9 cells were found to mount potent antitumor activity, which is suppressed in the absence of Foxo1, suggesting that Foxo1-mediated IL-9 induction is essential in mounting the potent antitumor immunity by Th9 cells." (PMID 29867972, 2018). "Importantly, we demonstrated that blocking IL-9 using a neutralizing anti-IL-9 mAb at the time of GITR stimulation abrogated the effects of anti-GITR mAb in protection against cancer in the lungs, thus establishing a key role for IL-9 in the anti-tumour immunity in this model." (PMID 26365427, 2015). "When the average tumor volume reached 30 mm3, mice were grouped to receive either Xcl1-E6E7 with or without the IL-9 plasmid." (PMID 39852828, 2025). "Moreover, another study showed that CD4+ T cells lacking Atg3 or Atg5 can increase IL-9 expression and autophagy inhibition enhanced T helper 9 cell anticancer effects in vivo, and mice with T cell-specific deletion of Atg5 showed decreased tumor outgrowth in an IL-9-dependent manner." (PMID 38627815, 2024). "In contrast, mice lacking mast cells, which express moderate levels of IL-9 in INFER mice, have increased tumor growth and did not have the same changes in macrophage populations observed when IL-9 or IL-9R are lost." (PMID 35778404, 2022). "By using cell counts, we found that IL-9 did not influence the tumor cell count, while IFN-ɣ and TNF-alpha decreased the overall tumor cell count." (PMID 35514957, 2022). "The description of specific compartmental effects of IL9 and IL18 in the stroma cannot be concluded without looking into the tumor compartment in comparison." (PMID 36131941, 2022).
tumor (continued). "Intriguingly, the expression of IL5 and IL9 was increased in ILC2s from PBMCs from NSCLC patients, but not in ILC2s from tumor tissues, compared with HD-derived PBMCs." (PMID 34194433, 2021). "To assess the role of IL-9 in the antitumor effects of FasL-TH9, we intravenously or subcutaneously challenged Il9r−/− mice with B16F10-OVA tumor cells and found that neither FasL-TH9 nor cTH9 enhanced antitumor immunity." (PMID 31266950, 2019). "It is not yet to know whether the IL-9 secreting T cells in low dose DCG spore treated mice are contributing the antitumour effect, as IFNγ has been shown to be critical for rejecting the tumour." (PMID 31183361, 2019). "To elucidate the role of IL-9 in the antitumor effects of these cells, we subcutaneously challenged Il9r−/− mice with B16F10-OVA tumor cells and found that neither FasL + p38i-TH9 nor FasL-TH9 could inhibit tumor progression." (PMID 31266950, 2019). "To dissect whether Fas signaling is related to TH9 cells in tumor-bearing mice, we injected B16F10 cells intravenously into WT mice and analyzed Il9 mRNA levels in Fas-positive and Fas-negative CD4+ T cells." (PMID 31266950, 2019). "Here, we think that the elevated IL-9 levels might be secreted by DLBCL cells themselves, and might also be produced by the non-malignant infiltrating cells within tumor tissues." (PMID 27364124, 2016). "Moreover, Th9/Th22 correlation was negative in EOCRC cohort, suggesting that IL-9-driven inflammatory signals may help restrain IL-22-mediated STAT3 activation and tumor-promoting self-renewal pathways." (PMID 41425582, 2025).
infection (127 papers, 2006 to 2026). The state of being infected such as from the introduction of a foreign agent such as serum, vaccine, antigenic substance or organism. "Infection by this pathogenic bacterium stimulates the secretion of excess interleukin-9 (IL-9), leading to increased goblet cell proliferation." (PMID 41323881, 2025). "In particular, the signature based on IL-2, IP-10, and IL-9 detection was associated with TB status (infection/disease)." (PMID 38076244, 2023). "We also identified immune/inflammatory response markers associated with aGVHD (IL-9, Eotaxin-3), cGVHD (Flt-1), infection (D-dimer), or relapse (IL-17D, bFGF, Eotaxin-3)." (PMID 35700185, 2022). "Severe infection with the acute respiratory syncytial virus was associated with elevated IL9 levels." (PMID 29937515, 2018). "By in vivo neutralization, we demonstrate that increased IL-9 production during the first days of infection caused accelerated mast cell degranulation and rapid expulsion of S. ratti adults from the small intestine of Treg-depleted BALB/c mice." (PMID 24516385, 2014). "Interestingly, we found that IL-9 enhanced infection of Omicron variant of SARS-CoV-2 in ACE2.Tg mice, as indicated by loss of body weight, increased lung lesions and viral load with increased infiltration of immune cells and lung tissue damage." (PMID 37429848, 2023). "A number of non-infection associated genes that encode secreted proteins with potential to influence the phenotype of the infected cell and/or cells of the host immune system were also identified (e.g. IL9, CXCL2, CLEC3B and ADAMTS19)." (PMID 35061738, 2022). "We measured the levels of IFN-gamma, IL-4, IL-10, IL-17A, IL-23, and IL-9 in the serum samples and PBMCs from the KO and WT mice at different stages of infection to conduct and extensive analysis of how USP21-deficient Tregs affect the resistance of mice to S. japonicum." (PMID 33628844, 2021). "For helminth infection in humans, the immune response during the early/acute phase of infection involves the induction of type 2-associated cytokines (IL-4, IL-5, IL-9, and IL-13) first by innate lymphocytes (ILC2) and later by effector antigen-specific polyfunctional CD4 T cells." (PMID 30416709, 2018). "Finally, we also confirm that Ss infections are associated with elevated levels of antigen-stimulated IL-9 levels by using ELISA." (PMID 26730582, 2016). "These parasites bias the immune response toward Th2 and/or a regulatory environment associated with high levels of IL-4, IL-13, IL-9, IL-5, and IL-10; also, infection with helminths compromises immunity to other unrelated infections and may also affect the efficacy of vaccines." (PMID 26090422, 2015). "While IL-10-producing Tfh expanded during infection, IL-9-producing cells and Th17 cells expanded mainly after treatment." (PMID 41823215, 2026). "The concentration of chemokines CxCL1/KC/GRO-α, CxCL2/MIP-2, CCL5/RANTES and cytokines TNF-α, IL-1β, IFN-γ, IL-5, IL-6, IL-9, IL-10, IL-13, IL-17, IL-23 circulating in blood were measured in experimental animals on day 15 post-infection." (PMID 40445994, 2025). "We found higher IL-1b levels in adult serum and PBMC cultures post-infection, correlating with age and promoting IL-6, IL-9, and IL-17A secretion when combined with IFNa." (PMID 40834853, 2025). "We began by investigating IL-9 levels in the pleura of naïve and L. sigmodontis-infected mice at 30 days post-infection (dpi), a stage where fourth-stage larvae molt into adult worms." (PMID 40962954, 2025). "IL-9 played a protective role against Helicobacter pylori and helped limit infection in mouse model." (PMID 36154925, 2023). "This aligns with the high IFNγ levels observed in our severely infected patients and the higher IFNγIL-9 ratio in patients who later died of infection, making this IFNγ/IL-9 ratio a novel marker of disease severity." (PMID 37569646, 2023).
infection (continued). "Taken together, our Data demonstrate that IL-9 promote SARS-CoV-2 infection, and make in Foxo1fl/fl.CD4Cre+ mice susceptible to infection." (PMID 37429848, 2023). "Conversely, infection significantly reduced levels of IL-1α, IL-2, IL-9, IL-10, IL-12 (p70), IL-13, IFNγ, IL-3, CCL4 (MIP-1β), CSF 2 (GM-CSF), CCL5 (RANTES), and TNFα." (PMID 37790429, 2023). "Severe cases showed a significantly stronger increase than mild patients in levels of all cytokines (except IL-9) and all gene expression on day 1 of infection." (PMID 37569646, 2023). "On the other hand, it was shown that NF-κB activation aided in infection eradication by triggering Th2 cytokine responses (mostly IL-9 and IL-13)." (PMID 37737322, 2023). "Given the importance of IFNγ in our predictive analysis and the association between IL-9 and survival, we analysed the kinetics of IFNγ/IL-9 ratio at the onset of infection." (PMID 37569646, 2023). "Pro-inflammatory IL-8(CXCL8), regulatory IL-10 and TH-2 type IL-9 cytokines were measured in serum samples of AE patients and infection-free controls using specific ELISA." (PMID 35108275, 2022). "IL9 overexpression also induced a nearly threefold reduction in CD3+ T lymphocytes at 14 days after CVB3 infection compared to controls (AAV9-Control: 1.2% CD3-stained cardiac area ± 0.2 vs. AAV9-IL9: 0.4% CD3-stained cardiac area ± 0.1, p < 0.001)." (PMID 35508525, 2022). "A more persistent effect on cardiac fibrosis and systolic function at 35 days post-infection required the combined expression of IL9 with IL3, IL4, IL13, and IL15." (PMID 35508525, 2022). "It is worth mentioning that the different effects of IL-9 appear to be parasite dependent based on a comparison with the effects of IL-9 neutralization after infection with Trichinella muris." (PMID 35597967, 2022). "In the lamina propria, a low expression of ST2 was observed, along with a small percentage of ST2+ IL-9- cells that remained unchanged with infection." (PMID 35711429, 2022). "In mouse models, IL-9 not only exerts inflammation by promoting this NLRP3 inflammasome during the initial stages of VVC but also increases tolerance against infection toward the recovery phase by inducing the IL-1 receptor antagonist." (PMID 36159646, 2022). "Previous studies have demonstrated that Haemonchus contortus excretory and secretory proteins (HcESPs) induce the proliferation of Th9 cells and alter the transcriptional level of IL-9 as well as its related pathways in the Th9 immune response after infection." (PMID 35597967, 2022). "During infection, the production of IL-9 and transcriptional levels of genes related to the TGF-β/Smad pathway gradually increased." (PMID 35597967, 2022). "Five of the forty markers tested were significantly increased in K1544Δcps-infected eyes 24 h after infection: IL9, IL10, IL12-p70, MIG, and MIP-1-gamma." (PMID 35456761, 2022). "Western blot results showed that the expression of NICD and the phosphorylation level of STAT3 were obviously decreased from LV-Notch1-shRNA infection group in IL-9 treated-astrocytes, compared to the LV-ctrl group." (PMID 33971906, 2021). "IL-9 treatment prior to cell infection with T. cruzi TCTs (pretreatment) significantly reduced the number of infected cells and intracellular parasites in the C2C12 myoblasts and bone marrow-derived macrophages." (PMID 34722343, 2021). "In vitro infection demonstrated that IL-9 reduced the number of infected cells and decreased the multiplication of intracellular amastigotes in both C2C12 myoblasts and bone marrow-derived macrophages." (PMID 34722343, 2021). "Based on additional studies in mice, demonstrating that ILC2-derived IL-9 triggers CF-associated inflammation via a complex vicious cycle that includes activation of mast cells, it was speculated that a similar mechanism could support the infection-dependent disease exacerbation in CF." (PMID 34177944, 2021).
infection (continued). "IL-6, IFN-γ, MIG, IL-17, and IL-9 are important inflammatory cytokines in the anti-infection immune response and were all increased in the blood of patients with AE-IPF in our cohort." (PMID 30718973, 2019). "It is conceivable that after infection, IL-9–producing T cells continue to reside locally in the skin." (PMID 30807238, 2019). "While IL-3 and IL-9 were decreased in both infection groups, IL-6 was only significantly decreased in T. canis-infected and GM-CSF only in T. cati-infected mice." (PMID 31315623, 2019). "This was also reflected in the similar IgG response seen at day 18 post-infection, which is a key indicator of Th1/2 balance, and IL-9 expression in mLN CD4+ T-cells at day 13 post-infection." (PMID 30998782, 2019). "Pathogen-specific responses were also observed for IL-6 and GM-CSF, which were significantly reduced during chronic NT in cerebra of only T. canis-infected or T. cati-infected mice, respectively, while IL-3 and IL-9 were decreased in both infection groups." (PMID 31315623, 2019). "IL-9 has been shown to act autocrinally to maintain lung ILC2s and to play a role in tissue repair after infection with N. brasiliensis." (PMID 30283458, 2018). "The expression of Il9 increased early and was observed throughout the infection in C57BL/6 mice, but was unaffected in Il9R−/− mice, a finding suggesting that IL-9 expression is IL-9R-dependent." (PMID 30515173, 2018). "The levels of the Th9 response indicate a significant induction of IL-9 after INMI1 infection which peaked at 72 h after INMI1 infection (p = 0.02)." (PMID 29967565, 2018). "Here we use IL-9 receptor deficient mice on BALB/c and C57BL/6 genetic background to dissect effector and regulatory functions of IL-9 during infection with the parasitic nematode Strongyloides ratti." (PMID 29872093, 2018). "IL-13 and IL-9 cytokine production by infection-primed lymphocytes was highest in response to stimulation with sub-groups 3 and 4, whereas the highest anti-parasite antibody levels were measured in response to sub-group 2." (PMID 29540816, 2018). "Serum of control, infected and infected/anti-IL-9 mAb-treated mice were collected on week 8 post infection." (PMID 28539607, 2017). "Immunofluorescence, qRT-PCR, and ELISA results demonstrated that the expression of IL-9 significantly increased after infection (P < 0.01)." (PMID 28539607, 2017). "We demonstrated that the IL-9+ lymphocyte population significantly expands in the liver of C57BL/6 mice during infection by S. japonicum." (PMID 28539607, 2017). "We looked therefore for the presence of IL-9+ILC2 and Th9 cells in infection by characterizing IL-9-producing Lin− and CD4+ T cells in the lung." (PMID 28090087, 2017). "Among HIV-infected individuals during chronic infection concentrations of IL-9 were significantly reduced when compared to the acute stage of infection." (PMID 27356504, 2016). "Drug cure resulted in a sudden decrease of most of the cytokines that became overexpressed after primary infection (IL-6, IL-9, IL-12, IL-33, IFN-γ and TSLP)." (PMID 27658962, 2016). "Comparison of cytokine expression between two stages of infection showed significant decrease in IL-9 concentration." (PMID 27356504, 2016). "We then compared IFNγ production by CD4+ and CD8+ T cells isolated from the lung, spleen and draining LNs of anti-IL-9-treated and isotype control antibody treated mice at day 7 post-infection." (PMID 25646821, 2015). "The results suggest that the production of IL-9 in chlamydial lung infection is redundant for host defense, at least in this primary infection model." (PMID 25646821, 2015). "We found significant increase of IL-9 producing CD45+ lymphocytes following infection at day 3 post-infection, in both percentages and absolute cell numbers." (PMID 25646821, 2015). "The results suggest that IL-9 production is redundant for host defense against chlamydial lung infection, at least in the primary infection model." (PMID 25646821, 2015).